KLF5 (KLF transcription factor 5)
Diseases named in the same sentence as KLF5 in open-access papers (continued):
Sharing a sentence is not in itself a finding about the gene and the disease.
cancer (continued). "Patients with copy number gains in KLF5 and ZFHX3 were at a 3.2-fold and 2.5-fold increased risk of cancer-specific mortality, respectively." (PMID 28915599, 2017). "Functionally, KLF5 promoted cancer cell proliferation, migration and invasiveness in a manner dependent partly on TNFRSF11a expression." (PMID 29146991, 2017). "Regulatory roles of KLF5 on cancer stemness have also been indicated in siRNA-mediated KLF5-knockdown experiments that have shown reduced numbers of CD44high/CD133high cells." (PMID 28757546, 2017). "Abundant evidences have demonstrated critical roles of KLF5 in regulating cell proliferation and migration/invasion in various cancers." (PMID 28749461, 2017). "Because it has been suggested that several cancer-promoting genes, such as Akt, c-Myc, KLF5, and DRD2 are involved in cell survival or proliferation in BCa cells, we sought to compare the status of these genes in human TNBC tumors versus non-TNBC tumors." (PMID 27283899, 2016). "Abundant evidence has demonstrated critical roles of KLF5 in regulating cell proliferation in various cancers, however, its additional roles in other aspects of cancer development remain to be further clarified." (PMID 26544730, 2015). "During a 1-month period, BAP1 and KLF5 knockdown cancer cells grew significantly slower than the Lucsh control cells." (PMID 26419610, 2015). "As in many other types of cancers, prostatic carcinogenesis depends on the accumulation of multiple genetic and epigenetic alterations, and deletions of KLF5 and PTEN can occur in the same tumors." (PMID 25896712, 2015). "Several genes, such as CD44, KLF5, K-Ras and hexokinase 2, have been confirmed as the direct targets of miR-143 in cancer cells." (PMID 26484567, 2015). "KLF5 (Krüppel-like factor 5) plays critical roles in normal and cancer cell proliferation through modulating cell cycle progression." (PMID 25170806, 2014). "Curcumin treatment or knockdown of KLF5 by lentivirus-shKLF5 down-regulated cyclin D1 expression and decreased cancer cell growth." (PMID 25170806, 2014). "On the other hand, KLF5 inhibits the proliferation of cancer cells including those from the esophagus, prostate, breast and epidermis." (PMID 23755247, 2013). "Deletion of KLF5 in human cancers is almost exclusively hemizygous, which reduces KLF5 transcription by half because KLF5 is haploinsufficient." (PMID 23755247, 2013). "This is consistent with the observations in hundreds of human prostate and other cancers, whereas hemizygous deletion at the KLF5 locus occurs in as frequently as 40% or more of cases, homozygous deletion is hardly detectable." (PMID 23755247, 2013). "Other miR-143 responsive genes with a miR-143 seed site in their 3'UTR were SEMA5A, SLC35B2 and KLF5 which have all been shown to be up-regulated in cancers and to promote cell proliferation." (PMID 22691140, 2012). "Although these results are consistent with the observations made in breast, prostate and esophageal cancer cell lines, data contradicting a Klf5 growth inhibitory role in transformed cells is also available." (PMID 20514221, 2009). "Among these 11 SEs, only the SEs associated with KLF5 and MYB were located within the genomic regions showing recurrent duplication, as observed in a high-resolution whole-genome sequencing dataset from the Pan-Cancer Atlas of Whole Genomes (PCAWG) Project." (PMID 40234694, 2025). "Targeting KLF5 in ARID1A-deficient cancer cells has a negative CRISPR score, which indicates ARID1A mutant cells are sensitive to KLF5 depletion." (PMID 39779698, 2025). "In addition, we analyzed the pan-cancer profile of PTMs of KLF5 and identified significant DNA hypomethylation across multiple cancer types." (PMID 41583492, 2025).
cancer (continued). "Within this framework, a focused pan-cancer analysis of KLF5 is warranted." (PMID 41583492, 2025). "KLF5 belongs to the Krüppel-like factor family, which are evolutionarily conserved zinc finger-containing transcription factors with multiple regulatory functions in diverse human cancers." (PMID 39827156, 2025). "Thus, a possibility exists that RUVBL1/2 is a therapeutic cancer target because it acts as a rate-limiting enzymatic coactivator required for the aberrant activity of TF oncoproteins such as KLF5." (PMID 41241675, 2025). "Collectively, we provide thorough exploration of KLF5 across various cancers." (PMID 41583492, 2025). "Meanwhile, KLF5 is a potential transcription factor targeting ferroptosis regulators in cancer." (PMID 39317954, 2024). "deAc-KLF5 upregulates TNF-α in cancer cells to increase FGF9 release by CAFs." (PMID 38781024, 2024). "Four genes, RAB10, KLF5, TCF7L2, and CTNNB1 had gene essentiality strongly correlated with both SMAD4 mutation and SMAD4 CNA in various cancer cells (i.e., genes that are more essential when SMAD4 copy number is decreased or when SMAD4 is mutated, P values inferior to 1E-04)." (PMID 37377893, 2023). "In our study, we observed that KLF5 may regulate DNA replication and spliceosome pathways, which are also abnormally altered and critical in cancer." (PMID 37702443, 2023). "It was speculated that TNF-α could induce the expression of the KLF5-EphA2 axis to promote cancer stemness." (PMID 37063424, 2023). "Targeting the KLF5/COX2/PGE2 axis may be an effective therapeutic strategy in diverse cancers, including BLBC." (PMID 36923542, 2023). "Thus, we accessed The Cancer Genome Atlas Program (TCGA) and Catalogue of Somatic Mutations in Cancer (COSMIC) databases and acquired a list of mutations in KLF4 and KLF5 in samples obtained from CRC patients." (PMID 37173904, 2023). "This growth dependency suggests KLF5 is an oncogene that drives cancer progression." (PMID 37239940, 2023). "KLF5 has been shown to promote cancer cell proliferation in various cancers." (PMID 37377893, 2023). "The KLF5 enhancer region plays a biologically important role in cancer stem-like properties." (PMID 34707247, 2022). "Notably, the heterodeletion mutants of KLF5 enhancer impaired the cancer stem-like properties of CRC cells." (PMID 34707247, 2022). "Cell survival and proliferation, proinflammatory cytokine expression and TGR5/STAT3/KLF5 axis activity were measured in normal human gastric cells, cancer cells, and organoid lines derived from C57BL/6, FVB/N and insulin-gastrin (INS-GAS) mice treated with DCA." (PMID 36067404, 2022). "Notably, an ILK inhibitor disrupts the α-Catulin-KLF5 interaction, promotes the degradation of KLF5, and decreases α-Catulin-driven cancer stemness." (PMID 35154481, 2022). "Overexpression of KLF5 partially rescues the OSU-T315-suppressed cancer sphere formation." (PMID 35154481, 2022). "Some miRNAs have been found to regulate KLF5 in certain cancers." (PMID 35836107, 2022). "KLF5 also plays an important role in disease development, especially in cancers." (PMID 35836107, 2022). "Establishing the critical role of the α-Catulin-KLF5 complex in promoting cancer cell stemness and resistance to chemotherapy may indicate that this complex is a molecular target for the therapy of human malignancies." (PMID 35154481, 2022). "Here, we mention the key role that KLF5 plays in cancer; although its role in cancer may differ from that in the heart, some parts of its role may help to link knowledge of both for further investigation in the future." (PMID 35457114, 2022). "Knockdown of KLF5 abrogates α-Catulin-driven cancer stemness." (PMID 35154481, 2022). "In other words, KLF5 may exert pro-cancer or anti-cancer functions depending on the different cancer types studied." (PMID 33923166, 2021).
cancer (continued). "Additionally, enhanced miR-21 expression promotes cancer cell migration and invasion by inhibiting Krüppel-like factor 5 (KLF5) in vitro." (PMID 33572780, 2021). "Transition between epithelial and mesenchymal morphologies upon changes in KLF5’s acetylation status in cancer cells could have important implications." (PMID 33731701, 2021). "We then manually checked KLF5 CNV across different cancer types using a genome browser." (PMID 33923166, 2021). "Therefore, KLF5 can play a role in many diseases, including, cancer, cardiovascular disease and gastrointestinal disorders." (PMID 33523554, 2021). "KLF5 expression and activity are altered in many human cancers." (PMID 33430300, 2021). "Therefore, by regulating the expression level of KLF5 or its coexpressed genes, the development of cancer can be inhibited." (PMID 34367275, 2021). "We first studied the CNV of KLF5 across a large series of cancer samples from TCGA dataset." (PMID 33923166, 2021). "Krupple-like factor 5 (KLF5) is a zinc-Finger transcription factor involved in many cellular functions such as differentiation, proliferation, migration, apoptosis and regulation of cancer stemness." (PMID 33424607, 2020). "The main purpose of our present study was to obtain a therapeutic miRNA that could suppress cancer stemness, and we focused on the KLF5 molecule as the main target." (PMID 32066912, 2020). "All the evidence indicates the importance of KLF5 activation in human cancer." (PMID 32460441, 2020). "As hypothesized, KLF5 expression was positively correlated with that of SNHG12 in both cancer and normal tissues." (PMID 32943987, 2020). "At present, research on KLF5 is mainly concentrated in the field of cancer." (PMID 31178864, 2019). "If patients on this trial were stratified for cancers that were dominant for signaling via the PrPC‐FOXO3a‐KLF5 axis they could be switched off FOLFOX therapy, resulting in high rates of survival." (PMID 30478887, 2019). "KLF5 has been reported to negatively regulate p27Kip1 transcription in cancer cells." (PMID 30770784, 2019). "Functional studies support KLF5 as an important cancer-related gene." (PMID 30038712, 2018). "In cancer cells, microRNA mir-143 and mir-153 directly inhibit the expression of KLF5." (PMID 30271790, 2018). "Klf5 generally acts as a transcriptional activator that is dysregulated in many cancers." (PMID 30038712, 2018). "Although the transcription factor Krüppel-like factor 5 (KLF5) plays important roles in both inflammation and cancer, the mechanism by which this factor promotes cervical carcinogenesis remains unclear." (PMID 29146991, 2017). "Hypoxia is a potent inducer of HIF1α, but it did not appear to be necessary for KLF5 loss to induce HIF1α, at least in cancer cell lines, because the morphological and molecular alterations in PC-3 and DU 145 cells were detected under normoxic conditions." (PMID 25896712, 2015). "Expression of KLF5 was found to be abnormal in many cancer types." (PMID 25988147, 2014). "Pursuing this hypothetic path, colonization of the metastatic site de facto implies proliferation and, therefore, may require downregulation of KLF5 in Ras-transformed cancer cells." (PMID 24429391, 2014). "Our results confirmed that YAP/TAZ is down-regulated by curcumin, and because they stabilize KLF5 in cancer cells, the decrease of YAP/TAZ may lead to the degradation of KLF5." (PMID 25170806, 2014). "We also demonstrated that lentivirus-based knockdown of KLF5 inhibited cancer cell growth, while over-expression of a Flag-tagged KLF5 could partially reverse the effects of curcumin on cell growth and cyclin D1 expression." (PMID 25170806, 2014). "In addition, knockdown of KLF5 in cancer cells increases their sensitivity to DNA damage and related cell death, which is associated with reduced BAD phosphorylation and downregulation of PIM1." (PMID 23755247, 2013). "Recently, in cancer, KLF5 has been shown to promote survivin expression." (PMID 21951574, 2011).
cancer (continued). "Moreover, the degradation of Klf5 was enhanced in cancer cell lines from breast and prostate as compared to the non-neoplastic cells." (PMID 20514221, 2009). "Therefore, a comprehensive profiling of KLF5 function in pan-cancer is necessary to address." (PMID 41583492, 2025). "Furthermore, KLF5 blockers in combination with ICBs may provide a novel therapy in cancer immunotherapy." (PMID 36923542, 2023). "However, the cell-extrinsic effects of KLF5 on suppressing the immune response to cancer remain unclear." (PMID 36923542, 2023). "In addition, KLF5 could regulate stemness, cell proliferation, apoptosis, autophagy or migration of cancer cells, depending on the types of cancer." (PMID 37400979, 2023). "Thus, blocking the Klf5/Cox2 pathway within cancer cells may increase the quantity and activity of antineoplastic T-cell populations, causing the expansion of Trm cells, which protect against tumorigenesis." (PMID 36923542, 2023). "The KLF5 stabilizing proteins, Yes-associated protein (YAP)/transcriptional coactivator with PDZ-binding motif (TAZ), that protect KLF5 from undergoing proteosomal degradation are less expressed as well, suggesting an involvement of the Hippo pathway in curcumin’s anti-cancer effects." (PMID 32466578, 2020). "For instance, transcription factors MGA and KLF5 harbor mutations within their basic helix-loop-helix and C2H2-ZF domains, respectively, that alter their DNA base-binding positions, suggesting cancer-specific changes to normal DNA-binding and downstream regulatory activity." (PMID 32711844, 2020). "Thus, it is important to identify KLF5 upstream positive regulators, which may be better therapeutic targets for cancer treatment." (PMID 26419610, 2015). "Taken together, these results suggest that RUVBL1/2 cooperates with KLF5 to activate transcriptional programs that define lineage identity in PDAC, and potentially other cancer types." (PMID 41241675, 2025). "Furthermore, we found that cancer cells exhibited dominant expression of the mutated alleles, including those in the proto-oncogene KRAS (e.g., c.35G>T in CRC07, c.436G>A in HTCRC01 and c.38G>A in HTCRC05), KLF5 (c.935C>T in CRC07) and PIK3CA (c.2836G>T in CRC09)." (PMID 40702779, 2025). "For example, SE amplifications increase the expression of oncogenes including MYC, SOX2, USP12, KLF5, ZFP36L2, thereby promoting the progression of various cancers, including endometrioma and gastrointestinal tumors." (PMID 40234694, 2025). "We explored the expression of the KLF5 mRNA in 30 paired samples of PDAC and para-carcinoma tissue from patients." (PMID 39827156, 2025). "Specifically, YB-1 promotes cancer cell proliferation by stabilizing specific m5C-modified mRNAs, such as HDGF and KLF5 mRNA." (PMID 39497723, 2024). "As previously reported, KLF5 cooperates with GATA4 and 6, forming cooperative transcriptional networks that regulate downstream targets in a cancer- and tissue-specific manner." (PMID 39456519, 2024). "As a zinc-finger transcriptional factor, Kruppel-like factor 5 (KLF5) is involved in the development of many diseases, especially in cancers and cardiovascular diseases." (PMID 38472369, 2024). "Interestingly, a specific human cancer-derived KLF5 is resistant to degradation, raising the possibility that, in response to higher levels of stress, this protein could direct cells that would normally undergo apoptosis to instead activate pro-survival pathways." (PMID 37130837, 2023). "KLF5 also plays a critical role in the EMT, which contributes to cancer cell invasion and metastasis." (PMID 37461162, 2023).
cancer (continued). "In summary, our results indicate the potential of the KLF5/COX2/PGE2 axis as a therapeutic target to improve the efficacy of ICBs in BCLC and other cancers." (PMID 36923542, 2023). "When KLF5 was knocked down in KrasG12D mice, PDAC progression significantly decelerated, suggesting a multifactorial regulation in cancer cell proliferation and survival." (PMID 37239940, 2023). "TEAD4 interacts with KLF5 (Kruppel Like Factor 5) to suppress CDK inhibitor p27 expression, resulting in the cancer cell growth." (PMID 35602596, 2022). "Moreover, KLF5 could promote cancer metastasis in a variety of cancer types." (PMID 35073911, 2022). "Then, we predicted and validated potential transcription factors (including E2F7, KLF5 and FOXM1) and therapeutic drugs (such as cyclophosphamide, vinblastine, and gefitinib) that target ferroptosis regulators in cancer." (PMID 34975326, 2022). "We found that CD44, CDK6, GATA4, GATA6, KLF5, and KRAS, which were amplified in TCGA STAD cohort, were amplified in cancer cell clusters." (PMID 35087207, 2022). "In cancer tissues, KLF5 expression was observed in the nucleus or cytoplasm, and CRC cancer samples were divided into three groups based on the nuclear staining as follows: weak: 7.4%, moderate: 37.0%, and strong: 55.6%." (PMID 34707247, 2022). "Besides, cancer-related metastasis may be facilitated by KLF5 in many cancer types." (PMID 36224562, 2022). "Downstream of SREBF1, a non-canonical, SCC-specific function is elucidated: SREBF1 cooperates with TP63/KLF5 to regulate hundreds of cis-regulatory elements across the SCC epigenome, which converge on activating cancer-promoting pathways." (PMID 34272396, 2021). "Krüppel-like factor 5 (KLF5) is a zinc-finger transcription factor, which regulates cell growth, proliferation, differentiation, and tumorigenesis in several cancers, including GC." (PMID 33718128, 2021). "Here, KLF5 was found to harbor a higher frequency and more support reads of integration breakpoints in PSCC than in other cancers." (PMID 34885212, 2021). "We finally obtained eight bona fide cancer driver genes, including CEP57, HNRNPL, KLF5, OXA1L, PAFAH1B1, RBM39, SYT13, and TFDP1." (PMID 31925297, 2020). "We further demonstrate that a SE‐associated ce‐lncRNA, LINC00094 can be activated by transcription factors TCF3 and KLF5 through binding to SE regions and promoted ESCC cancer cell growth." (PMID 32460441, 2020). "This is of interest, since Cyclin D1 is a downstream target gene of Krüppel-like factor 5 (KLF5), which in cancer is up-regulated as a part of Wnt signaling in a β-catenin-dependent manner." (PMID 32466578, 2020). "Our study examined KLF5's involvement in EAC, an intestinal-like cancer that develops in a squamous cell environment." (PMID 31401336, 2019). "These instances are listed in the Dataset EV2 and they included, among others, RBL2, KLF5, and ARAF as homologs of cancer drivers RB1, PBX1, and BRAF, respectively." (PMID 29572294, 2018). "We also found that c-JUN facilitates expression of pluripotent genes, such as Klf5, Zfp42, Dppa4 and Esrrb, which is consistent with previous observations that c-JUN plays a pivotal role in the maintenance of self-renewal in cancer stem cells." (PMID 27894081, 2017). "When we overexpressed KLF5 in HCC1937 cells, the metformin-induced cancer stem cell decrease was partially rescued." (PMID 28480051, 2017). "Further analysis of clinical specimens suggested that expression of KLF5 and BIRC5 is up-regulated during the progression from inflammation to cancer." (PMID 26474386, 2015). "Furthermore, in a subset of these cancers (ACC, GBM, LGG, LUAD, PAAD, and THYM), KLF5 expression served as a predictor with high accuracy for both OS and DSS, as demonstrated by ROC analysis." (PMID 41583492, 2025).